MACC1 (MET transcriptional regulator MACC1)
Diseases named in the same sentence as MACC1 in open-access papers (continued):
Sharing a sentence is not in itself a finding about the gene and the disease.
head and neck cancer (1 paper, 2024). A primary or metastatic malignant neoplasm affecting the head and neck. "Interestingly, in head and neck cancer the expression of MACC1 was found to be higher in CSC when compared to cancer cells." (PMID 39580452, 2024).
head and neck squamous cell carcinoma (1 paper, 2024). A squamous cell carcinoma that arises from any of the following anatomic sites: lip and oral cavity, nasal cavity, paranasal sinuses, pharynx, larynx, and salivary glands. "In ESCC, coexpression of MACC1 with Snail and AGR2, along with diminished KAI1, is associated with LNM in ESCC and head and neck squamous cell carcinoma (HNSCC)." (PMID 39399490, 2024).
Hearing impairment (1 paper, 2023). A decreased magnitude of the sensory perception of sound. "Although MACC1 expression is associated with highly malignant tumors and VS are considered benign, both are attached to the HGF/MET signaling pathway and MACC1 is a candidate gene localized at a hearing loss-related gene locus." (PMID 37627117, 2023). "Since MACC1 has the ability to enhance cell invasiveness and it was identified as a candidate gene localized at the autosomal recessive non-syndromic hearing impairment locus DFNB90 mapping to 7p22.1-p15.3, its association with hearing loss was hypothesized." (PMID 37627117, 2023). "Interestingly, MACC1 was identified as a candidate gene localized at the autosomal recessive non-syndromic hearing impairment locus DFNB90, and therefore suggests its association with hearing loss." (PMID 37627117, 2023). "In addition, the putative involvement of MACC1 in the loss of hearing and hearing impairment as a pivotal characteristic of VS was the rationale to investigate whether MACC1 might be involved in VS pathogenesis." (PMID 37627117, 2023). "In addition, MACC1 may be associated with nonsyndromic hearing impairment." (PMID 37627117, 2023).
intestinal tumors (1 paper, 2022). "Additionally, we examined the ApcMin mouse model of APC/β-catenin-dependent intestinal tumors for susceptibility of such effects of MACC1 in vivo by means of IHC and RT-qPCR." (PMID 36008464, 2022).
Lymphatic Metastasis (1 paper, 2021). Transfer of a neoplasm from its primary site to lymph nodes or to distant parts of the body by way of the lymphatic system. "In multivariate analysis, the OR (95% CI) of MACC1 expression was 1.5 (1.1 to 2.0) in patients with lymphatic metastasis versus non-lymphatic metastasis after adjusting all variables." (PMID 34343214, 2021).
pleural cancer (1 paper, 2018). A primary or metastatic malignant neoplasm affecting the pleura. "For example, MACC1 is associated with pancreatic EMT and metastasis, which the analysis found for both pancreatic and pleural cancer cell lines, while suggesting the opposite effect in lung, endometrium, and upper digestive tract cancers." (PMID 29293502, 2018).
schwannoma (1 paper, 2024). A benign, usually encapsulated slow growing tumor composed of Schwann cells. "Generally, the expression of MACC1 has been detected in multiple different cancers, however it is not limited to aggressive tumors but can also be found in Schwannomas or benign colon adenomas." (PMID 39580452, 2024).
serous carcinomas (1 paper, 2018). "MACC1 mRNA high expression was significantly related to poor PFS in 483 serous carcinomas (HR = 1.45 (95% CI: 1.16 – 1.82), P = 0.0013) and in 494 patients with stage III or IV (HR = 1.50 (95% CI: 1.21 – 1.86), P = 0.00024)." (PMID 30515418, 2018).
serous ovarian cancer (1 paper, 2024). "In this article, we present a protocol for lentiviral transduction of EOC organoids, with a particular focus on the knockdown of the metastasis-associated in colon cancer 1 (MACC1) gene in representative high-grade serous ovarian cancer (HGSOC) lines, the most common and most aggressive form of EOC." (PMID 39728624, 2024). "In the search for potential novel biomarkers for early detection and disease management, we here show, for the first time, the successful lentiviral integration of shRNA targeting MACC1 into the genome of two high-grade serous ovarian cancer organoid lines." (PMID 39728624, 2024).
somatotropinoma (1 paper, 2020). "Our data indicated that three genes having pronounced effects on tumorigenesis were strongly downregulated by SSA/DA in somatotropinoma tissues (MUC16, MACC1, and GRHL2) and confirmed these findings in functional GH3 cell experiments." (PMID 33680922, 2020).
tongue squamous cell carcinoma (1 paper, 2022). A squamous cell carcinoma that arises from the tongue. "Similarly, it was also demonstrated to stimulate tumor development through miR-876-3p/MACC1 axis by serving as an emulative endogenous RNA in patients with tongue squamous cell carcinoma (TSCC)." (PMID 35873495, 2022).
tubular adenoma (1 paper, 2016). A usually polypoid neoplasm arising from the glandular epithelium. "To further pinpoint specific occurrence of MACC1 in patients’ bloodstream, we included samples from normal, hyperplastic and tubular adenoma patients." (PMID 27439755, 2016). "MACC1 transcripts were detected at a significant higher level in the combined group of hyperplastic and tubular adenoma patients’ plasma when compared to lesions-free patients’ plasma (p = 0.014)." (PMID 27439755, 2016). "Significance was also reached when comparing lesion-free patients’ MACC1 transcripts to the group of tubular adenoma patients (p = 0.011)." (PMID 27439755, 2016). "Blood samples (n = 93) from normal (n = 45), hyperplastic (n = 15) and tubular adenoma (n = 33) patients were used to assess MACC1 transcripts using qRT-PCR." (PMID 27439755, 2016). "Taken together, the levels of circulating MACC1 transcripts in plasma of at least patients with tubular adenoma are higher than in lesion-free volunteers and might indicate those patients at high risk for tumor progression." (PMID 27439755, 2016).
urothelial carcinoma (1 paper, 2014). A malignant neoplasm derived from the transitional epithelium of the urinary tract (urinary bladder, ureter, urethra, or renal pelvis). "It would be interesting in the future to explore the downstream signaling events responsible for MACC1-mediated tumorigenesis in urothelial carcinoma." (PMID 24949951, 2014).
virus infections (1 paper, 2025). "In cervical cells harboring the HPV sequences in an inflammatory environment, the MACC1 gene expression could be involved in virus infections." (PMID 40361484, 2025).
tumor (140 papers, 2011 to 2026). "A second study in breast cancer confirmed the positive effect of MACC1 on the infiltration of macrophages, in this case, specifically of anti-inflammatory, tumor-associated macrophages (TAMs)." (PMID 38611008, 2024). "The tEx[miR] group showed the lowest expression of MACC-1, a marker associated with tumor progression and metastasis." (PMID 39273182, 2024). "Taken together, this newly discovered MACC1—LGR5 association contributes to better understanding of the stemness-tumor progression/metastasis link." (PMID 38339354, 2024). "In terms of cellular responses relevant to cancer, MACC1 has primarily been implicated in cell migration, an important event during tumor dissemination, but is also involved in other events including cell adhesion." (PMID 38396744, 2024). "Metastasis-associated colon cancer-1 (MACC1) has been identified in various solid tumors and is closely associated with tumor progression, invasion, and metastasis." (PMID 38818465, 2024). "The upregulation of MACC1 expression has been linked to advanced tumor stages, lymph node metastasis, and distant metastasis, with an incidence rate of 72.9% in CRC patients." (PMID 39273182, 2024). "Bioinformatic analysis followed by Kaplan Meier survival analysis in TNBC patients identified Metastasis associated colon cancer 1 (Macc1) as one of the top candidate genes mediating the aggressive phenotype in the T1 tumor cells." (PMID 37841442, 2023). "Analysis of clinicopathological parameters of ESCC patients showed that MACC1-positive expression was associated with tumor size (P = 0.02)." (PMID 35242498, 2022). "MACC1 expression levels were associated with the tumor CMS subtypes (median: CMS1 = 10.1, CMS2 = 10.8, CMS3 = 10.2, CMS4 = 10.6, Kruskal–Wallis test p = 1.6 × 10−6)." (PMID 35406521, 2022). "As we and others reported previously, there is an association between high MACC1 mRNA levels and clinical markers of aggressiveness, such as higher tumor stages or nodal invasion." (PMID 35406521, 2022). "The combined MACC1/S100A4 biomarker robustly identified CRC patients at high risk for poor MFS by tumor RNA analysis and predicted poor OS from liquid biopsy analyses." (PMID 36008464, 2022). "In Kazakh patients, MACC1-positive expression was associated with tumor size (P = 0.03) and tumor invasion depth (P = 0.02)." (PMID 35242498, 2022). "Metastasis-associated in colon cancer-1 (MACC1) is a novel prognostic, predictive, and causal biomarker for tumor progression and metastasis in many cancer types." (PMID 35242498, 2022). "Positive MACC1 expression was associated with tumor size in Han patients with ESCC (P = 0.03, P < 0.05) and invasive depth (P = 0.03P < 0.05) which were significantly associated." (PMID 35242498, 2022). "High expression of MACC1 was significantly associated with worse tumor differentiation (P = .04), more advanced FIGO stage (P < .01) and earlier lymph node metastasis (P < .01) compared to low expression of MACC1." (PMID 33663046, 2021). "The gene Metastasis-associated in colon cancer 1 (MACC1) was newly discovered in our group and is a key regulator of metastasis as well as a prognostic and predictive marker in many tumor entities." (PMID 33652667, 2021). "Metastasis-associated in colon cancer 1 (MACC1) protein has been implicated in tumor invasion, migration and in epithelial-mesenchymal transition (EMT)." (PMID 33854976, 2021). "High expression of MACC1 is significantly associated with tumor metastasis and poor clinical outcome, and is an early risk factor for cancer patients." (PMID 33712897, 2021). "Accumulating evidence of in vivo and in vitro studies indicated that high expression of MACC1 was strongly associated with tumor formation, metastases development and poor prognosis." (PMID 33750337, 2021). "The higher MACC1 expression levels in the SW480/MACC1-derived tumor tissue are also associated with a stronger iron staining, compared to SW480/e.v.-derived tumors." (PMID 33469705, 2021).
tumor (continued). "Metastasis Associated in Colon Cancer-1 (MACC1) has been shown to modulate tumor cell growth and activate invasion and metastasis, mainly by activation of the HGF/MET oncogenic pathway." (PMID 33731131, 2021). "MACC1 has been well known as a key oncogenesis regulator and biomarker of tumor metastasis in a broad panel of cancer entities, associated with poor prognosis." (PMID 34221989, 2021). "Mutating the MACC1 tyrosine phosphorylation sites, results in diminished tumor growth and metastasis in mice." (PMID 34247190, 2021). "High MACC1 expression was significantly associated with poor prognostic parameters, such as larger tumor size, grade III tumors, positive nodal metastasis, lymphovascular invasion, stage III tumors, and elevated Ki-67 expression." (PMID 34577857, 2021). "The MACC1 rs1990172 "CA + AA" polymorphic variants are associated with lower risk of clinical stage, tumor size, and vascular invasion in HCC patients among smokers." (PMID 32047570, 2020). "Elevated MACC1 expression has been demonstrated to be associated with tumor oncogenesis, metastasis and worse prognosis, as well as regarded as an early risk factor for cancer patients 1-6." (PMID 32174779, 2020). "Among tremendous kinds of tumor promoting antigens, metastasis-associated in colon cancer 1 (MACC1) has been found to play pivotal roles in cancer tumorigenesis and metastasis, and its relevance in chemoresistance has also been reported." (PMID 30805302, 2019). "Currently, exosomal circ-PDE8A was reported to be associated with tumor progression and lymphatic invasion by the miR-338/MACC1/MET pathway in pancreatic ductal adenocarcinoma." (PMID 31277663, 2019). "Metastasis-associated in colon cancer 1 (MACC1) has been reported to promote tumor cell invasion and metastasis." (PMID 30021598, 2018). "The mechanism behind the effect of XIST on cell growth and invasion in GC, involves sequestration of the tumor suppressor miR-497, which targets the oncogene Metastasis Associated in Colon Cancer 1 (MACC1)." (PMID 30018188, 2018). "LncRNA XIST expression was negatively associated with miR-497 expression, while positively associated with MACC1 expression in the tumor tissues." (PMID 27911852, 2017). "Consistent with our findings, a separate study associated increased MACC1 in tumor tissues with progressive factors, such as Ki-67 status, TNM stage, tumor size, and lymph node status, excluding ER and HER2 status." (PMID 27793048, 2016). "Our previous studies have demonstrated that overexpression of metastasis associated with the colon cancer 1 (MACC1) predicted poor prognosis of GC and promoted tumor cells proliferation and invasion." (PMID 27581375, 2016). "Metastasis-associated in colon cancer-1 (MACC1) is key in promoting tumor proliferation and invasion, and is mediated by the hepatocyte growth factor (HGF) and mesenchymal-epithelial transition factor." (PMID 25295116, 2014). "Metastasis-associated in colon cancer 1 (MACC1) is a newly identified gene that has been shown to promote tumor cell invasion and metastasis." (PMID 25009663, 2014). "We further investigated if down-regulation of MACC1 expression was associated with tumor cell apoptosis and cycle by using flow cytometric analysis." (PMID 23414367, 2013). "Metastasis-associated in colon cancer-1(MACC1), a new gene associated with primary and metastatic colon cancer, promotes tumor cell growth as well as the development of distant metastasis." (PMID 23414367, 2013). "Above results indicate that expression of MACC1 are associated with tumor cell proliferation and apoptosis." (PMID 23414367, 2013). "A higher expression of MACC1 mRNA was significantly associated with ages, tumor size, portal vein trunk invasion, multinodular and poorly tumor differentiation, but not with gender, lesion number, AFP level or Child-Pugh class." (PMID 23414367, 2013).
tumor (continued). "Further efforts should be made in order to evaluate if the MACC1 SNPs are germline or somatic polymorphisms and if they occur in other tumor entities." (PMID 22838389, 2012). "Although the evaluation of invasiveness was out of the scope of this study, MACC1 has been shown to correlate with further invasiveness of tumor cells and therefore might be relevant for hearing impairment caused by tumor invasiveness." (PMID 37627117, 2023). "Thus, many upstream and downstream targets of MACC1 were identified and associated with typical tumor features such as NANOG and OCT4 with dedifferentiation, VEGF, and TWIST1/2 with angiogenesis." (PMID 37051546, 2023). "The promoter activity and gene expression of MACC1 can be influenced by genetic polymorphisms, which may potentially affect tumor growth, invasion, or metastasis 43-46." (PMID 38021160, 2023). "Higher MACC1 mRNA levels were positively correlated with CD163+ tumor-associated macrophages (r = 0.614, p < 0.001), and were negatively correlated with CD56+ natural killer cells (r = −0.398, p < 0.001) and CD8+ cytotoxic T lymphocytes (r = −0.323, p < 0.001)." (PMID 34577857, 2021). "MACC1 is a causal driver of tumor progression and metastasis." (PMID 32670264, 2020). "One such driver of tumor progression is the gene Metastasis-Associated in Colon Cancer 1 (MACC1)." (PMID 32670264, 2020). "The results showed that in 151 HCC patients among smokers who carried MACC1 rs1990172 "CA + AA" variants had a lower risk of developing a large tumor (odds ratio [OR] = 0.375, p = 0.026), more advanced clinical stage ([OR] = 0.390, p=0.032), and vascular invasion ([OR] = 0.198, p = 0.034)." (PMID 32047570, 2020). "Furthermore, we observed an association between MACC1 overexpression and several clinicopathological parameters (patient age, tumor size, patient gender, cancer localization, tumor grade, TNM stage, nodal status, tumor depth, and distant metastases)." (PMID 27542234, 2016). "In addition, further studies have demonstrated that MACC1 is associated with the proliferation, invasion, metastasis, and survival of tumor cells in these cancer types." (PMID 26043756, 2015). "In addition, we performed multivariate Cox regression combining MACC1 expression level with the tumor characteristics KRAS G12 or G13 mutation, BRAF V600 mutation and MSI status." (PMID 25742883, 2015). "Furthermore, nuclear MACC1 expression at the time of cryoablation was not only strongly associated with larger tumor size and poorly differentiation, but also associated with poor outcome in these patients." (PMID 23414367, 2013). "There are two death domain family (DD) domains at the MACC1 N-terminus, one of which is strongly associated with the programmed death of cells and plays a role in the development of inflammation, autoimmune modulation, the directional migration of tumor cells, and other functions." (PMID 36979146, 2023). "Interestingly, MACC1 overexpression in any geographic region of CRC was significantly associated with high grade tumor budding at the invasive front and aggressive histopathological features including more advanced pT and pN-stages, venous and lymphatic invasion." (PMID 25884643, 2015). "MACC1 expression was significantly associated with metastasis status and tumor stage, whereas MMP8 expression was associated with tumor localization." (PMID 42193101, 2026). "In MACC1-driven CRC, GIPC1 acts as protein interaction partner and as transcription factor of MACC1, playing a dual role in tumor progression and metastasis." (PMID 41522336, 2026). "Studies have demonstrated that MACC1 overexpression leads to increased tumor cell proliferation and metastasis." (PMID 40354443, 2025). "The identification of MACC1 as a target of tumor-suppressing miR-143 in CRC was established via in silico prediction and a Western blot assay." (PMID 41450965, 2025).